NOD1 (nucleotide binding oligomerization domain containing 1)
Diseases named in the same sentence as NOD1 in open-access papers (continued):
Sharing a sentence is not in itself a finding about the gene and the disease.
breast carcinoma (continued). "ETBF promoted breast cancer cell stemness and chemoresistance by secreting BFT-1, which bound to NOD1." (PMID 38437016, 2024). "NOD1 inhibition and ETBF clearance significantly increased the efficacy of DTX by suppressing BCSCs in breast cancer." (PMID 38437016, 2024). "Overall, these data indicate that NOD1, as a functional receptor, is stabilized by BFT-1 and mediates the biological function of BFT-1 secreted by ETBF in breast cancer." (PMID 38437016, 2024). "Modulation of these pathways leading to an increase in migration and invasiveness in breast cancer cells, supports the phenotype of increased colony formation potential previously observed in HS578T/NOD1." (PMID 30791886, 2019). "In the present study, we examined the effects of NOD1 and NOD2 overexpression towards the global proteome of breast cancer-derived Hs578T cells." (PMID 30791886, 2019). "We have previously shown that overexpression of either NOD1 and NOD2 innate immune receptors impacts cell proliferation and clonogenic potential of the triple negative, breast cancer-derived Hs578T cell line." (PMID 30791886, 2019). "Although NOD1 tumor suppressive role is evidenced in ER-dependent tumors, both NOD1 and NOD2 appear to be relevant for the aggressive potential of breast cancer in vitro." (PMID 30837326, 2019). "To better delineate this issue, we investigated NOD1 and NOD2 expression in a panel of breast cancer cell lines, as well as their potential impact in breast tumorigenesis based on in vitro assays." (PMID 29615116, 2018). "The Nod1 signalling complex has been shown to drive JNKactivation, cytokine release, and induction of apoptosis in MCF7 breast cancer cells." (PMID 26678268, 2015). "NOD1 functions as a sensitizer of the TNF signaling pathway, facilitating cellular apoptosis and significantly downregulating estrogen receptor expression in breast cancer cells, thereby impeding the initiation and progression of breast cancer." (PMID 39329913, 2024). "We examined the mechanisms by which NOD1 downregulated NUMB and observed that the mRNA expression level of NUMB was not affected by NOD1 in breast cancer cells." (PMID 38437016, 2024). "Although no tumor suppressor activity has been described for NOD2, NOD1 seems to have important tumor suppressor activity in estrogen receptor (ER)-dependent breast cancer, using an SCID mice xenograft model." (PMID 30837326, 2019). "Also, NOD1 activation was shown to promote apoptosis and reduce estrogen-induced proliferative responses in the estrogen-dependent MCF7 breast cancer cell line." (PMID 30791886, 2019). "In order to determine whether NOD1 and/or NOD2 play significant roles in the onset and progression of breast cancer, here we evaluated the expression of NOD1 and NOD2 in a panel of progressively invasive breast cancer-derived cell lineages." (PMID 29615116, 2018). "In addition, we analyzed the impact of NOD1 and NOD2 overexpression in breast cancer, based on cell proliferation and clonogenic assays." (PMID 29615116, 2018). "NOD1 inhibition by Nodinitib-1 together with ETBF clearance by metronidazole (MNZ) increased the chemosensitivity of breast cancer by targeting breast cancer stem cells (BCSCs), providing a promising therapeutic rationale to overcome chemoresistance in breast cancer." (PMID 38437016, 2024). "Here, we show that NOD1 and NOD2 display variable expression levels in a panel of estrogen receptor-positive and estrogen receptor-negative breast cancer cell lines." (PMID 29615116, 2018). "Some investigators suggested that NOD1 and NOD2 inflammasomes may also be relevant to the negative regulation of breast cancer." (PMID 37020871, 2023).
asthma (19 papers, 2009 to 2025). "After these first genetic studies, several authors have confirmed the link between NOD1 gene polymorphisms and haplotypic combinations with atopy and asthma development in different populations." (PMID 36189256, 2022). "A systematic search of polymorphic alleles in DNA obtained from blood, described for the first time NOD1 polymorphisms associated with asthma and high levels of seric IgE." (PMID 36189256, 2022). "The NOD1 gene is located in the 7q14-p15 chromosome region, a locus previously identified by different genome-wide association analyses as an atopy and asthma-related trait susceptibility locus." (PMID 36189256, 2022). "The SNP on NOD1 identified in children was found to be associated with asthma protection in a European cohort." (PMID 33546184, 2021). "Nevertheless, NOD1 polymorphisms have been associated with the development of atopic eczema, asthma and increased serum IgE concentration, while polymorphisms in the intronic region of NOD1 have been linked with the age of IBD onset." (PMID 28611823, 2017). "Single nucleotide polymorphisms in Nod1 gene were positively associated with susceptibility towards asthma in farming children and this PRR was reported to be necessary for neutrophil function in mice." (PMID 24735374, 2014). "Insertion-deletion polymorphisms in the NOD1 gene have been associated with increased risk of developing asthma, and genetic variations in NOD1 that affected microbial recognition were positively associated with disease susceptibility and pathogenesis." (PMID 23781124, 2013). "Single nucleotide polymorphisms in the Nod1 gene were positively associated with susceptibility towards asthma in children living on farms, and this PRR has been reported to be necessary for neutrophil function in mice." (PMID 23781124, 2013). "Diseases associated with NOD1 activity are mostly chronic inflammatory disorders, e.g., atopic eczema and asthma, underscoring the importance of this receptor in the regulation of the immune response, this includes NF-κB activation, cytokine production and, interestingly the induction of apoptosis." (PMID 23028889, 2012). "In accordance with these results, our group has shown that both NOD1 deficient and RIPK2 deficient mice, when subjected to an HDM asthma protocol, present reduced asthma features including reduced AHR, eosinophil, and neutrophil recruitment." (PMID 36189256, 2022). "In agreement with the genetic link to asthma and the adaptive immune modulation role of NOD1, our group has reported that a NOD1 agonist can exert adjuvant effects exacerbating the asthmatic response in an OVA-induced Th2-mediated allergic model." (PMID 36189256, 2022). "In contrast, NOD1, as well as RIPK2 adaptor deficiency, strongly downregulated all the features of HDM-induced asthma." (PMID 36233196, 2022). "using NOD1 haplotype tagging SNPs in DNA obtained from children’s blood samples, found that 21596 T SNP in NOD1 can drastically modify the effect of environmental factors in asthma, correlating with higher frequencies of atopic asthma symptoms." (PMID 36189256, 2022). "Many of the diseases accompanied by high NOD1 activity are chronic inflammatory disorders, such as asthma and atopic eczema, emphasizing the critical role of this receptor in regulating the immune response." (PMID 29760746, 2018). "The BIRC2 and BIRC3 genes (which had altered expressions in ASD, asthma, ear infection, and bacterial and viral infections) are members of the inhibitor-of-apoptosis protein family and are key regulators of NOD1 and NOD2 innate immunity signaling." (PMID 27842596, 2016). "However, no direct associations between Tlr3 and Nod1 expression and function and asthma have been reported yet, and whether the decreased mRNA expression of Tlr3 and Nod1 caused by the chronic inflammatory status of the animals is pro-inflammatory or anti-inflammatory is also unknown." (PMID 24735374, 2014).
asthma (continued). "As PRRs in the lung can modulate ongoing chronic inflammation during asthma, the mRNA expression of Tlr1-9 and Nod1-2 were measured." (PMID 24735374, 2014). "As PRRs in the lung can modulate ongoing chronic inflammation during asthma, the mRNA expression of Tlr1-13 and Nod1 and 2 was measured." (PMID 23781124, 2013). "In regard to genes encoding CARD-containing proteins, mutations in the peptidoglycan receptors NOD1 and NOD2 have been associated to several inflammatory disorders, including Crohn's disease, Blau syndrome and asthma." (PMID 19859543, 2009). "Altogether, these data suggest that, as is the case for NOD1, NOD2 ligands contained in pathogens or vaccines may potentially lead to increased susceptibility to asthma development or the worsening of asthma." (PMID 36233196, 2022). "Dysregulated expression of the truncated NOD1 isoform upon inflammatory stimulations could ultimately contribute to different disease states in asthma development." (PMID 33546184, 2021). "However, differential expression of some asthma genes was consistent in both developing human and murine lung, e.g. NOD1, EDN1, CCL5, RORA and HLA-G." (PMID 21699702, 2011). "NOD1/CARD4 and is located on chromosome 7p14 that has been genetically linked to asthma." (PMID 19723304, 2009). "Furthermore, a recent mouse asthma model revealed that HDM-associated Gram-negative bacteria aggravated disease severity through nucleotide-binding oligomerization domain-containing protein 1 (NOD1)." (PMID 37252681, 2023). "Indeed, despite the NOD1 deficient mice presenting dysbiotic gut microbiota, the transplantation of the NOD1 deficient microbiota into WT mice did not result in any significant changes in the HDM experimental asthma model outcome." (PMID 36189256, 2022). "However, no direct associations between Nod1 expression and function and asthma have been reported yet." (PMID 23781124, 2013). "Genetic variations in NLRC1 (NOD1), though not serving as direct genetic markers of disease, may be more closely associated with an elevated susceptibility to ulcerative colitis, arthritis, asthma, and Behçet’s syndrome." (PMID 37869013, 2023). "RIPK2 is the downstream adaptive protein in both the NOD1 and NOD2 signaling pathways, and as such, is a critical mediator in the NOD1 and NOD2-related implication in asthma development." (PMID 36189256, 2022). "Despite this fact, the reported results seem to indicate that there are differences in the implication of NOD1 and NOD2 in the lung epithelium in the context of asthma." (PMID 36189256, 2022). "Different experimental models have been used to explore and confirm the findings obtained in human samples and in vitro studies regarding the implication of NOD1 and NOD2 in different aspects related to asthma pathophysiology." (PMID 36189256, 2022). "Among genes identified in asthma GWAS, ROBO1, RORA, HLA-DQB1, IL2RB and PDE10A showed most consistent expression patterns and from asthma candidate genes, e.g. NOD1, EDN1, CCL5 and HLA-G were identified." (PMID 21699702, 2011). "In the context of asthma, although many NLR functions and mechanisms are still unknown, it is now clear that at least some of them, namely NOD1, NOD2, and NLRP3, play crucial roles in the development, regulation, and exacerbation of asthma." (PMID 36189256, 2022). "The relevant role of NOD1 and NOD2 not only in asthma but also in other diseases with an inflammatory component, such as Crohn ́s disease, has encouraged the development of different compounds with the ability to target their signaling pathways, mainly the adaptor protein RIPK2." (PMID 36189256, 2022). "NOD1 and NOD2, as sensors of microorganisms and cellular stress, have been identified as potential therapeutic targets in a range of autoimmune and autoinflammatory disorders and in diabetes, asthma, atherosclerosis, various forms of CNS diseases and even cancer." (PMID 40666513, 2025).
asthma (continued). "Moreover, the HDM in vitro stimulation of NOD1 knockdown human bronchial epithelial cells further supported the higher relevance of NOD1 compared with NOD2, in the aggravation of asthma most likely via the differential expression of agonist transporters at the respiratory epithelium." (PMID 36189256, 2022). "While there was no general over-representation of asthma genes among differentially expressed genes, some asthma genes were consistently differentially expressed in multiple developing lung transcriptomes, e.g. NOD1, EDN1, CCL5, RORA and HLA-G suggesting key functional roles in lung development." (PMID 21699702, 2011). "However, Nod1 was not represented on the platforms used for analyses on the A/J and SW strains and could thus not be evaluated in these data sets (also true for another asthma gene with consistent expression patterns, PCDH1)." (PMID 21699702, 2011).
colon carcinoma (19 papers, 2013 to 2025). "In a mouse model of colon carcinogenesis, NOD1 deficiency facilitates colon tumor development from colitis, and depleting the microbiota slows tumor progression in mice." (PMID 38437016, 2024). "Upon combination of a single hit of the carcinogen, azoxymethane (AOM), with DSS, NOD1-deficient mice were found to develop significantly more and larger colonic tumors as compared to WT mice." (PMID 25071785, 2014). "A previous study reported that colon tumours are associated with high NOD1 protein levels." (PMID 36068649, 2022). "TLR4 and TLR2 enhance metastasis of colon cancers, whereas NOD1 promotes several gastrointestinal malignancies such as colon cancer, as well as head and neck and oral squamous cell carcinoma." (PMID 35130902, 2022). "This protein is involved in the ubiquitin–proteasome pathway and was previously reported to promote NOD1 degradation, thus limiting NOD1-mediated apoptosis, NF-κB activation and inflammation in the colon carcinoma cell line." (PMID 32365813, 2020). "Stable knockdown (KD) of NOD1 in human colon cancer cells (HT29) was constructed with shRNA lentiviral transduction and the functional assays were thus repeated." (PMID 31956962, 2020). "NOD1 expression in paired human primary colon cancer, human and murine colon cancer cells were determined using immunohistochemistry and immunoblotting (WB)." (PMID 31956962, 2020). "Despite its ubiquitous expression in colonic tumors and liver metastases, the clinical impact of NOD1 need to be established." (PMID 31956962, 2020). "In this study, we have, for the first time, established a direct link between NOD1 activation and metastasis of colon cancer." (PMID 31956962, 2020). "Using a series of in vivo and in vitro experiments, we determine that the increase in colon cancer adhesion, migration and metastasis is augmented by NOD1 activation via the p38 MAPK pathway." (PMID 31956962, 2020). "Although we clearly demonstrated that NOD1 activation increases the migratory phenotype of colon cancer cells in vitro, we sought to confirm its role in promoting a metastatic phenotype in a more physiologically relevant in vivo model." (PMID 31956962, 2020). "Having determined NOD1 expression and its clinical impact on colon cancer survival at the clinical level, its mechanistic role in metastasis is investigated through its activation and inhibition in a series of functional assays." (PMID 31956962, 2020). "Intriguingly, it has been reported that treatment with low doses of DSS leads to increased colonic tumors in ApcMin/+Nod1−/−mice suggesting that NOD1 serves as a negative regulator of the tumor-promoting Wnt/β-catenin cascade." (PMID 25071785, 2014). "However, recent studies show that NOD1 is involved in tumorigenesis and is negatively correlated with colon cancer patient survival." (PMID 38437016, 2024). "NOD1 signaling has been shown to be protective against colon tumor development in both AOM-DSS and ApcMin/+ models, where NOD1 plays a pivotal role in maintaining the intestinal epithelial barrier against chemically induced chronic injury, as in the case of these mouse models." (PMID 37519301, 2023). "Furthermore, NOD1 has been reported to be involved in the development of many cancers, such as breast and colon cancer." (PMID 36675746, 2022). "Although NOD1 expression is elevated in colon tumors and liver metastases, whether these elevated expressions exert any clinical significance in patients with CRC remains unproven." (PMID 31956962, 2020). "Indeed, with NOD1 activation, we observed a significant increase in in vitro static adhesion of human colon cancer cells HT29 to fibronectin (2-fold), collagen I (2-fold) and collagen IV (1.5-fold) compared to baseline DMSO control (P < 0.0001)." (PMID 31956962, 2020). "Hence, after confirming the clinical significance of NOD1 over-expression in colon cancer, direct evidence on whether NOD1 activation augments metastasis was investigated." (PMID 31956962, 2020).
colon carcinoma (continued). "Similarly, NOD1 activation promotes colon cancer growth and metastasis." (PMID 31186453, 2019). "The in vivo effects of NOD1 activation with C12 and co-incubation with ML130 were assessed by injecting thus treated murine MC38 colon cancer cells intrasplenically into wildtype C57BL6 mice." (PMID 31956962, 2020). "Moreover, NOD1 also exerts a protective role against chronic intestinal inflammatory processes, like colorectal cancer as deduced from NOD1 or RIPK2 deficient mice challenged with different colonic tumor inducers, proving its role in the maintenance of intestinal homeostasis." (PMID 32704052, 2020). "In addition, multiple colon cancer cell lines of both human and murine origin, including HT29 and MC38, are also shown to express abundant amounts of NOD1." (PMID 31956962, 2020). "To test whether ER stress specifically induces NLRP1 gene expression, we stimulated HCT116 human colon cancer cells with various inflammatory stimuli and measured mRNA expression of both NLRP1 and NOD1 (NLRC1), which is another human NLR family member." (PMID 26086088, 2015). "The complete selectivity of GSK669 and GSK400 towards inhibition of NOD2 but not NOD1-mediated IL-8 secretion was also evident in HCT116 colon carcinoma cells which endogenously express both NOD1 and NOD2." (PMID 23936340, 2013). "Intertumoral activation of NOD1 by the gram-negative bacterial peptidoglycan gTri-DAP can enhance the immunosuppressive activity of myeloid cells to foster a tumor-permissive microenvironment in colon cancer." (PMID 38437016, 2024).